GFAP (glial fibrillary acidic protein)
Diseases named in the same sentence as GFAP in open-access papers (continued):
Sharing a sentence is not in itself a finding about the gene and the disease.
cognitive decline (133 papers, 2011 to 2026). "Previous studies have shown that higher plasma GFAP is associated with global cognitive decline in older adults." (PMID 40877465, 2026). "Our study extends these findings by demonstrating that longitudinal increases in plasma GFAP are associated with accelerated cognitive declines specifically in the domains of processing speed and visual attention among a relatively young cohort." (PMID 40877465, 2026). "In particular, we highlight that dynamic changes in pTau217, GFAP, and NfL are associated with cognitive decline and clinical progression and that a substantial proportion of individuals with SCD convert to biomarker positivity over time." (PMID 41335440, 2025). "Our main findings are that longitudinal increases in pTau217, GFAP, and NfL were strongly associated with cognitive decline over time, with pTau217 and GFAP slopes adding prognostic value beyond demographics and baseline biomarker values for progression." (PMID 41335440, 2025). "Increased plasma GFAP levels have also been associated with accelerated cognitive decline across different stages of disease severity, supporting its role in monitoring disease progression." (PMID 40690136, 2025). "Current evidence therefore suggests that plasma pTau, GFAP, and NfL are associated with brain amyloid deposition and cognitive decline in MCI‐LB." (PMID 40156325, 2025). "Longitudinal increases in pTau217 and GFAP were associated with cognitive decline over time in all domains (β time × biomarker slope = −0.02 to −0.04)." (PMID 41335440, 2025). "Plasma GFAP appears to have better predictive power for amyloid positivity than CSF GFAP and other glial markers and is associated with both cognitive decline and tau accumulation over time." (PMID 41465278, 2025). "Another 16-year longitudinal study linked higher serum GFAP levels with sporadic AD development, cognitive decline, and structural brain changes, emphasising its potential for tracking disease progression." (PMID 40690136, 2025). "Elevated plasma GFAP levels have been consistently associated with preclinical and symptomatic AD, demonstrating strong correlations with Aβ deposition and cognitive decline." (PMID 40690136, 2025). "BPV was also associated with plasma GFAP, a marker of neuroinflammation, neurodegeneration, and reactive astrogliosis that is associated with cortical volume loss, and cognitive decline." (PMID 39098984, 2025). "Similar to pTau217, GFAP and its changes over time showed strong associations with cognitive decline and clinical progression." (PMID 41335440, 2025). "This aligns with the existing literature showing that GFAP levels are associated with AD, cognitive decline, and amyloid beta plaques, which are all thought to be associated with lower neurogenesis levels." (PMID 40871708, 2025). "This study found that higher levels of neurodegeneration (t-tau), axonal injury (NfL), and reactive astrocytes and neuroinflammation (GFAP) biomarkers were associated with accelerated cognitive decline in genetically susceptible APOE4 carriers." (PMID 40332937, 2025). "Another study revealed that plasma levels of GFAP are associated with AD tau pathology and with cognitive decline." (PMID 41291905, 2025). "Cortical GFAP expression was strongly associated with amyloid pathology, tau pathology, and a faster rate of cognitive decline." (PMID 39580758, 2024). "In patients with HF, the relationship between pTau181 and GFAP and baseline memory performance remained, while associations with cognitive decline over time lost significance." (PMID 38489178, 2024). "A 5-year longitudinal study involving 169 individuals with MCI showed that higher baseline plasma GFAP concentrations were associated with the progression to AD and faster rates of cognitive decline." (PMID 39080712, 2024).
cognitive decline (continued). "Our results support previous biomarker findings and suggest that higher brain GFAP levels are associated with higher brain amyloid burden and faster cognitive decline among amyloid-positive individuals." (PMID 39580758, 2024). "Plasma p-tau biomarkers, particularly p-tau217, are known to associate with Aβ and tau pathologies and predict cognitive decline, while plasma GFAP associates with Aβ pathology, and neurofilament light with neuronal injury." (PMID 38109077, 2024). "Glial fibrillary acidic protein and phosphorylated tau 181 were associated with cognitive decline in amyloid positive individuals." (PMID 39291164, 2024). "In our study, CD8+ TEMRAs, previously linked to AD-related cognitive decline defined by CSF AD-biomarkers, cognition, and imaging, correlate with plasma biomarkers of brain injury (Nf-L and GFAP)." (PMID 38867294, 2024). "The association between GFAP and cognitive decline over time suggests that cognitive decline in patients with cardiovascular diseases is not solely associated with amyloid and tau burden, as represented by pTau181, but also with neuro-inflammation." (PMID 38489178, 2024). "A greater annualized rate of change in GFAP was significantly associated with faster global cognitive decline." (PMID 38735950, 2024). "Higher GFAP concentrations are linked to Aβ plaque density and white matter injury, correlating with cognitive decline." (PMID 39596011, 2024). "Higher baseline serum GFAP was associated with trajectories of cognitive decline on MMSE and all tests assessing memory, attention, and executive functioning, whereas higher NFL levels were not." (PMID 38994939, 2024). "Our findings reinforce the significance of GFAP as a biomarker for identifying CU individuals at risk for cognitive decline and AD progression." (PMID 38994939, 2024). "Yet, higher blood levels of both NFL and GFAP have been associated with reduced cognitive capacity and greater prospective cognitive decline." (PMID 38803456, 2024). "Our study unveils for the first time that CSF GFAP can predict AD-associated pathological changes and later cognitive decline and transformation in new-onset PD patients." (PMID 37475029, 2023). "The primary objective is to determine the correlation between CSF GFAP and cognitive decline across various domains, as well as AD-associated CSF biomarkers." (PMID 37475029, 2023). "Plasma GFAP concentration has been correlated with cortical amyloid status derived from 18F-flutemetamol amyloid PET scans, and the longitudinal change in GFAP was associated to the development of clinical AD and cognitive decline." (PMID 37924152, 2023). "In ALS patients, plasma GFAP was higher than in controls (p < 0.001) and associated with measures of cognitive decline." (PMID 37762278, 2023). "In the present study, we examined the cross-sectional and longitudinal associations of CSF GFAP with cognitive decline and changes in CSF biomarkers." (PMID 37475029, 2023). "One study found that plasma GFAP levels were significantly associated with cognitive performance in a cohort including individuals with subjective cognitive decline, MCI, and AD." (PMID 37932720, 2023). "In this outpatient memory clinic-based study, we examined the performance of two promising biomarkers of neurodegeneration and neuroinflammation, NfL, and GFAP, for the diagnostic work-up of patients along the continuum of AD-related cognitive decline." (PMID 36072480, 2022). "In conclusion, this study highlights the utility of blood‐based biomarkers, with a particular emphasis on plasma p‐tau217, in detecting Aβ/tau stages, GFAP‐mediated Aβ‐induced tau progression, and NfL‐associated non‐AD‐specific neuronal injury and cognitive decline." (PMID 41376134, 2025). "Furthermore, elevated plasma GFAP levels were significantly associated with faster cognitive decline among APOE ε4 carriers, suggesting a high vulnerability of astrocytosis and neuroinflammation in genetically high-risk groups." (PMID 40690136, 2025).
cognitive decline (continued). "The association between NfL and GFAP with cognitive decline in MCI is less well established." (PMID 40156325, 2025). "Although plasma p‐tau217, GFAP, and NfL exhibit considerable potential in the context of AD, there is a paucity of studies that concurrently examine their associations with brain Aβ/tau burdens and stages, hippocampal atrophy, and cognitive decline." (PMID 41376134, 2025). "Additionally, increased blood GFAP levels have been linked to cognitive decline and the prognosis of AD." (PMID 40690136, 2025). "Across demographically and clinically heterogeneous cohorts, plasma GFAP is a key moderator of AD and may help identify individuals at greatest risk of AD‐related neurodegeneration and cognitive decline." (PMID 40911721, 2025). "Beyond Aβ alone, plasma GFAP may provide additional prognostic information for identifying individuals at greatest risk for imminent disease progression and cognitive decline." (PMID 40911721, 2025). "Recently, plasma glial fibrillary acidic protein (GFAP), an intermediate filament protein of astrocytes, has been demonstrated to be associated with brain amyloid status and the development of clinical AD and cognitive decline." (PMID 38654932, 2024). "Additionally, higher levels of P-tau181 (β = −0.49 [95% CI: −0.71 to 0.26]), NfL (β = −0.29 [95% CI: −0.52 to 0.06]), and GFAP (β = −0.60 [95% CI: −0.83 to 0.38]) were linked to faster cognitive decline." (PMID 39253733, 2024). "Indeed, cortical GFAP was associated with worse global cognition at the final visit before death and a faster rate of cognitive decline in the years preceding death." (PMID 39580758, 2024). "Also, elevated GFAP was associated with worse cognition, and plasma GFAP was the most predictive of future cognitive decline." (PMID 38994939, 2024). "Furthermore, we refined our mixed model by integrating follow-up durations as random slopes, which reinforced the finding that higher rates of GFAP accumulation were significantly linked to accelerated cognitive decline." (PMID 38735950, 2024). "Significant associations between elevated GFAP levels and cognitive decline have been reported in female patients with long-COVID, whereas another study has documented lower GFAP levels in the blood of long-COVID individuals also experiencing persistent headaches." (PMID 38541055, 2024). "We found accelerated annual change in GFAP was significantly associated with more rapid cognitive decline (model 3, estimate = − 0.101, 95% CI = 0.163 to − 0.040), and the interaction between GFAP expression and follow-up time was not statistically significant." (PMID 38735950, 2024). "To this end, we sought to interrogate the relationship between GFAP transcript expression and protein abundance in the brain with multiple AD-relevant outcomes, including amyloid and tau pathology as well as cognitive decline, while also assessing associations with concomitant pathways of injury." (PMID 39580758, 2024). "GFAP, NfL, and/or p‐tau181 were elevated among all diseases compared to controls, and were broadly associated with worse baseline cognitive performance, greater cognitive decline, and/or lower functional independence." (PMID 38105605, 2024). "Similarly, in Parkinson’s disease, higher GFAP levels are associated with more severe motor dysfunction and cognitive decline, making it a potential marker for disease severity." (PMID 39063050, 2024). "The baseline value of GFAP may help to identify patients at risk of rapid cognitive decline in future clinical trials to reduce heterogeneity." (PMID 37475029, 2023). "Besides, the current investigation presumed a linear association between GFAP and future cognitive decline, as well as alterations in AD-related pathological markers in individuals with newly diagnosed PD." (PMID 37475029, 2023).
cognitive decline (continued). "Additionally, in the DIO mouse model, GFAP expression in the prefrontal cortex, which is one of the regions in the brain linked to cognitive decline observed in obesity, was lower in DIO mice treated with CYR119 than in the DIO-control mice." (PMID 34537066, 2021). "Notably, plasma p‐tau217 demonstrated a strong capacity for differentiating between Aβ/tau stages; abnormal plasma GFAP appeared to facilitate Aβ‐induced tau progression, whereas plasma NfL wa more closely associated with non‐AD‐specific neuronal injury and cognitive decline." (PMID 41376134, 2025). "To conclude, the observed reduction in plasma GFAP levels after following the O-BN diet for 3 months suggests that this diet may help mitigate factors that are strongly associated with neuroinflammation and cognitive decline." (PMID 39275164, 2024). "Previous studies found GFAP to be a potential prognostic biomarker, correlating with cognitive decline." (PMID 40684252, 2025). "A recent study identified plasma glial fibrillary acidic protein (GFAP) as a novel biomarker of cognitive decline in PWH." (PMID 40110851, 2025). "In the case of metabolic disorders, such as T2D, HbA1c is a crucial glycemic control and cognitive decline biomarker, whereas plasma GFAP and NfL are neuroinflammation and axonal damage indicators in T2D and obesity." (PMID 40842786, 2025). "Investigation of cognitive decline in AD should account for GFAP activity in assessing mechanisms of resilience." (PMID 39868232, 2025). "Longitudinally, baseline p-tau181 and GFAP levels best predicted cognitive decline at 0-2, 2-5, 5-10, and >10 years." (PMID 41534107, 2025). "GFAP has been proposed as a potential predictive biomarker of cognitive decline in patients with PD, particularly in the tremor-dominant (TD) subtype." (PMID 41465278, 2025). "The decrease in sample size is a result of include NfL and GFAP in the inclusion criteria, as these markers are indicative of a higher probability of cognitive decline." (PMID 38755703, 2024). "Plasma NfL and GFAP predict cognitive decline in a similar manner to traditional imaging techniques in amyloid-positive MCI patients." (PMID 38755703, 2024). "The present study showed that hepcidin depletion in GFAP-positive cells during development induced hippocampal atrophy and cognitive decline in mice." (PMID 38195497, 2024). "Studies also show that higher baseline GFAP concentrations are associated with the progression of MCI to AD and faster cognitive decline." (PMID 39596011, 2024). "Serum NFL and GFAP predicted clinical progression to MCI or AD from subjective cognitive decline, and GFAP further predicted MMSE slope longitudinally." (PMID 38994939, 2024). "Higher cortical GFAP levels were associated with increased amyloid pathology, CAA pathology, and faster cognitive decline (all PFDR < 3.3e−3)." (PMID 39580758, 2024). "Subgroup analysis with amyloid-positive MCI participants also showed that only NfL and GFAP were the only significant predictors of cognitive decline among plasma biomarkers." (PMID 38755703, 2024). "The first objective is to summarize the prognostic value of blood GFAP levels in predicting the future progression of cognitive decline in cognitively unimpaired individuals or those with MCI." (PMID 38439065, 2024). "Elevated GFAP levels correlate with cognitive decline and brain atrophy, providing a non-invasive method to track disease progression." (PMID 39063050, 2024). "In individuals with MCI, plasma GFAP levels can predict the development and cognitive decline of AD, as well as cognitive decline in CU individuals." (PMID 39594648, 2024). "In HF, blood-based biomarkers associated with AD, such as beta-amyloid, tau, glial fibrillary acidic protein (GFAP), and neurofilament-light can foreshadow cognitive decline and correlate to the severity of HF." (PMID 39452073, 2024). "Research has demonstrated a correlation between amyloid-β burden, cognitive decline, and plasma GFAP." (PMID 38902659, 2024).
cognitive decline (continued). "Research has demonstrated that CSF GFAP can predict AD-related pathological changes and cognitive decline in new-onset PD patients." (PMID 39720731, 2024). "In this systematic review and meta-analysis, we propose analyzing longitudinal studies on blood GFAP levels to predict future cognitive decline." (PMID 38439065, 2024). "The study found that plasma GFAP levels were associated with both longitudinal Aβ-PET deposition and cognitive decline." (PMID 39080712, 2024). "We observed that higher cortical GFAP expression correlates with worse global cognition at the visit prior to death and a faster rate of cognitive decline." (PMID 39580758, 2024). "p-tau181 and GFAP were the most important plasma predictors for predicting cognitive decline and their contribution increased with age." (PMID 39291164, 2024). "Elevated levels of NfL and GFAP have been observed in subjective cognitive decline (SCD), MCI and AD dementia." (PMID 37723371, 2024). "Elevations in GFAP, NF-L, and PRDX-6 point to a cycle of BBB disruption, axonal injury, oxidative stress, and neuroinflammation—factors that are closely linked to cognitive decline and neurodegenerative diseases." (PMID 39766495, 2024). "Plasma GFAP was highly accurate in predicting AD in patients with subjective symptoms or objective signs of cognitive decline, in line with the emerging literature." (PMID 37723371, 2024). "Elevated levels of glial fibrillary acidic protein (GFAP) in plasma reflect neuroinflammation and are linked to cognitive decline." (PMID 39275164, 2024). "A similar predictive role of plasma GFAP on cognitive decline has also been reported in patients with AD and MCI." (PMID 37932720, 2023). "Hereby, we chose to adjust for age, gender, baseline cognitive level, APOE ε4 carrying status and Aβ status for further investigation, and eventually found that there was still a predominant relationship between CSF GFAP and cognitive decline." (PMID 37475029, 2023). "Our findings indicate that GFAP is of potential clinical utility in screening amyloid pathology and predicting future cognitive decline." (PMID 37924152, 2023). "Subgroup analyses were conducted to further investigate the longitudinal relationship between GFAP and cognitive decline using GLMM adjusted for age, sex, education, APOE ε4 carrier status, and disease duration." (PMID 37475029, 2023). "The results demonstrated that plasma GFAP is a reliable indicator of cognitive decline, while NfL captured both cognitive decline and disease severity in both the PDND and PDD groups." (PMID 37480401, 2023). "As a marker for reactive astrocytes, GFAP is observed to be elevated after TBI and is associated with abnormal neuroimaging as well as cognitive decline in military personnel with severe TBI." (PMID 38292036, 2023). "Higher baseline CSF GFAP predicted greater global cognitive decline over time in early PD patients (Montreal Cognitive Assessment, β = − 0.013, p = 0.014)." (PMID 37475029, 2023). "Moreover, the unexpected strong association between synaptic density and GFAP+ astrogliosis suggested that beyond direct Aβ toxicity, chronically reactive astrocytes not only fail to protect synapses, but also detrimentally impair them and lead to cognitive decline." (PMID 32082319, 2020). "Strikingly, we observed a modest but significant correlation between GFAP levels and all measures of cognitive decline." (PMID 32514860, 2020). "Prominent astrogliosis and microgliosis with increased GFAP and Iba1 expression are common hallmarks of AD-related neuroinflammation, which contributes to the cognitive decline in AD." (PMID 29973867, 2018). "Similarly, the rate of cognitive decline was accelerated in only APOE4 carriers with upper tertile GFAP levels (eTable 2 and eFigure 3 in Supplement 1)." (PMID 40332937, 2025). "Similarly, we found a significantly faster rate of cognitive decline in APOE4 carriers with higher blood-based GFAP levels." (PMID 40332937, 2025).